CXCL12 (C-X-C motif chemokine ligand 12)
Diseases named in the same sentence as CXCL12 in open-access papers (continued):
Sharing a sentence is not in itself a finding about the gene and the disease.
breast carcinoma (continued). "MiRs targeting CXCL12 were transferred via gap junctions from bone marrow stromal to breast cancer cells resulting in decreased CXCL12 levels and reduced proliferation thereby promoting cancer cell quiescence." (PMID 28148265, 2017). "In this study, we demonstrated the significant inhibitory effects of a novel chemically synthetic peptide (E5) on the CXCR4/CXCL12 axis in breast cancer both in vitro and in vivo." (PMID 29263923, 2017). "GRK3 is a critical determinant of cellular responses to proliferative and migration signals through CXCL12/CXCR4 in breast cancer." (PMID 29445249, 2017). "Further, in vivo neutralization of the CXCL12/CXCR4 interaction in breast cancer has been shown to significantly inhibit lung and lymph node metastasis." (PMID 28055968, 2017). "The chemokine system CXCL12/CXCR4 crucially regulates metastatic dissemination of breast cancer cells." (PMID 29100413, 2017). "Among these factors, IL-6 and CXCL12 have been reported to promote cell growth in prostate and breast cancer respectively." (PMID 28258248, 2017). "While CXCR4 is expressed in many cancers including breast cancer, melanoma, and colorectal cancer, little is known about the regulation of its ligand, CXCL12." (PMID 29037250, 2017). "E5 was capable of specifically binding to the murine breast cancer cell line 4T1, remarkably inhibiting CXCL12- or stromal cell (MS-5)-induced migration, and adhesion and sensitizing 4T1 cells to multiple chemotherapeutic drugs." (PMID 29263923, 2017). "Taken together, our results showed that at least COL1A1, ACTA2, and FAP were significantly upregulated on mRNA levels in CAS from canine mammary carcinoma similar to human mammary carcinoma samples, whereas CXCL12 is downregulated." (PMID 28531107, 2017). "In summary, this is the first report demonstrating the expression of both CXCL16 and CXCL12 in CAFs derived from human breast cancer metastasis in the brain." (PMID 28649646, 2017). "Intriguingly, CAFs secreted higher levels of CXCL12 than the breast cancer cell line MCF-7, which promoted tumour growth and angiogenesis through the recruitment of endothelial progenitor cells." (PMID 27782035, 2016). "Stromal fibroblasts present in invasive human breast carcinomas promote tumor growth through elevated SDF-1/CXCL12 secretion, and lung stromal fibroblast-derived periostin creates a metastatic niche for breast CSCs." (PMID 26980947, 2016). "Our data emphasize the functional relationship of GRK3 as it pertains to CXCL12/CXCR4 migration in breast cancer and specific molecular subtypes." (PMID 27049755, 2016). "The use of highly specific inhibitors of E-selectin inhibited entry of breast cancer cells into the vascular niche, whereas inhibition of the CXCR-4/CXCL-12 axis induced mobilisation of dormant breast cancer cells from the vascular niche into circulation." (PMID 27782035, 2016). "Remarkably, mouse CXCL12 gene expression followed a similar pattern, suggesting again the importance of the cross-talk between the breast cancer cells and the cells in the microenvironment in the regulation of tumor spreading." (PMID 27806339, 2016). "This pathway is amplified in breast cancer cells by the action of Src in the presence of CXCL12/SDF-1 and IGF1 in bone marrow." (PMID 27486983, 2016). "Fibroblasts often constitute the majority of the stromal cells, and CAF extracted from invasive human breast cancer promotes tumor growth and angiogenesis through CXCL12 secretion in a mouse model." (PMID 27136535, 2016). "CXCL12 is highly expressed at common sites of breast cancer metastasis, such as the lymph nodes, liver, bone marrow, and lungs, and CXCR4 on tumor cells is critical for growth and migration." (PMID 27049755, 2016). "The G protein coupled receptors (GPCR), such as CXCR4, and its chemokine ligand CXCL12, have been identified as important regulators of metastasis and tumor behavior in breast cancer." (PMID 27049755, 2016).
breast carcinoma (continued). "In human breast cancer, activation of CXCL12/CXCR4 pathway induces the chemotaxis, invasion and metastasis of tumor cells." (PMID 27007162, 2016). "Autocrine stimulation from secreted CXCL12 has been shown to influence tumor behavior and phenotype, and CXCL12 expression in breast cancer cells has been correlated with decreased metastatic potential in humans." (PMID 27049755, 2016). "We do not know how FAK is activated by the feed-forward loop of KLF8/CXCR4 in response to CXCL12 stimulation in the breast cancer cells used in this study." (PMID 26993780, 2016). "Taken together, our results support a critical role of CXCR4 engagement by CXCL12 downstream of KLF8 for breast cancer metastasis." (PMID 26993780, 2016). "One important pathway that has been shown to be involved in breast cancer dissemination to distant organs is the CXCL12/CXCR4 axis; however, in our brain metastasis models neither of these genes showed significant changes." (PMID 27447568, 2016). "This is supported by a previous study, whereby intracellular Src enhanced PI3K-AKT signalling through stromal CXCL12, resulting in increased breast cancer metastasis to the bone marrow." (PMID 27782035, 2016). "The metastatic potential of breast cancer cells is acutely sensitive to regulation of the CXCL12/CXCR4 signaling axis governed by receptor expression, desensitization, internalization, and recycling dynamics." (PMID 27049755, 2016). "In preclinical mouse models, antagonists or neutralizing antibodies of CXCL12/CXCR4 axis as potential therapeutic reagents have been shown to reduce LN metastasis of breast cancer cells and melanoma cells." (PMID 28036019, 2016). "Taken together, these results point to a potentially important feed-forward signaling wheel consisting of KLF8, CXCR4 and FAK and CXCL12 is a critical driving force for the cycling of the wheel in breast cancer cells." (PMID 26993780, 2016). "In the context of breast cancer, chemokines have been implicated in promoting the malignant phenotype: CXCL3, CXCL12, CXCL13, CCL21 and CCL5 are associated with tumour progression and metastasis in breast cancer." (PMID 27335323, 2016). "In breast cancer, CAFs promote cancer cell growth, angiogenesis, and invasion by C-X-C motif chemokine 12 (CXCL12), MMP9, and MMP14." (PMID 26954362, 2016). "The CXCR4/CXCL12 axis has been thoroughly investigated and these two factors are upregulated in breast cancer cell lines as well as the most common sites of breast cancer metastasis." (PMID 26313265, 2015). "Next, we examined co-dependent gene expression relationships between CXCR7 and CXCR4, since in breast cancer cells CXCR7 is known to regulate CXCL12-mediated cell motility by modulating CXCR4 expression." (PMID 25884570, 2015). "The up-regulation of CXCR4 is a key to enhancing the CXCL12-dependent migration of breast cancer cells." (PMID 26413813, 2015). "We also revealed that, while basal-type breast cancer cells MDA-MB-157 showed CXCL12-induced migration, this migration was blocked by pre-treatment with GANT61." (PMID 26413813, 2015). "The CXCL12/CXCR4 axis is particularly important for homing of breast cancer cells to metastatic sites, including bone and lung." (PMID 26106384, 2015). "In this study, we showed that ANGPTL2 significantly up-regulated CXCR4 expression in breast cancer cells, which likely enhances their responsiveness to CXCL12." (PMID 25773070, 2015). "CXCL12 has been previously identified as an estrogen-regulated gene in estrogen receptor (ER)-positive ovarian and breast cancer cells." (PMID 25957946, 2015). "Although this study did not determine distant metastasis and relapses after treatment, considerable knowledge regarding CXCR4 role in breast cancer metastasis to CXCL12 producing organs has emerged." (PMID 26576337, 2015). "Müller and co-workers were the first to demonstrate CXCR4-mediated metastasis of breast cancer cells to CXCL12-rich environments, like bone marrow, brain, lungs and liver." (PMID 26396176, 2015).
breast carcinoma (continued). "Bone tissue-derived CXCL12 preferentially recruits breast cancer cells expressing CXCR4 to bone metastatic sites." (PMID 25773070, 2015). "It has also been experimentally confirmed that the CXCR4 up-regulation enhanced the chemoattraction or directional migration of breast cancer cells to CXCL12 in vitro, as well as the lung metastasis in vivo." (PMID 26413813, 2015). "CAF-derived chemokine SDF-1 (CXCL-12) is reported to recruit endothelial progenitor cells into breast carcinomas to induce angiogenesis." (PMID 25853091, 2015). "Assuming therefore that GLI1 up-regulates a set of these CXCL12-related signaling components in breast cancer cells, we focused our study on CXCR4, CXCR7 and LCP1." (PMID 26413813, 2015). "Here, we show that tumor cell-derived angiopoietin-like protein 2 (ANGPTL2) increases responsiveness of breast cancer cells to CXCL12 by promoting up-regulation of CXCR4 in those cells." (PMID 25773070, 2015). "CXCR4 positive breast cancer cells have been shown to metastasize to CXCL12 expressing organs as their first destination." (PMID 26055698, 2015). "CAFs from breast cancer promote angiogenesis by recruiting endothelial progenitor cells through secretion of SDF-1 (CXCL-12)." (PMID 26690480, 2015). "The present study demonstrated that the expression of CXCR4 was higher in the MCF7-GFP-NLP cells compared with the MCF7-GFP control cells, which implied that Nlp improved the migration capacity of breast cancer cell lines through activated CXCL12 and CXCR4." (PMID 25901761, 2015). "Intriguingly, CXCR4 co-expressed with CXCR7 enhances more CXCL12-induced migration and lung metastasis of breast cancer cells than the sole expression of CXCR4." (PMID 26413813, 2015). "Using anti-human CXCR4 monoclonal antibody, the immunoreactivity of membrane and cytoplasm was evaluated in breast cancer and correlated to sites of metastasis, particularly in CXCL12-producing organs." (PMID 26161302, 2015). "It has been found that CXCR4 is required for breast cancer cell migration to other sites such as lung, bone, and lymph nodes, which express high levels of CXCL12 chemokine." (PMID 26161302, 2015). "In conclusion, tranilast affects CXCL12/ CXCR4 axis that lead to suppress invasion of breast cancer cells." (PMID 25237365, 2014). "These inhibitory mechanisms are distinct from those we defined in colorectal or mammary carcinoma and suggest CXCL12 is a tumor suppressive cellular brake limiting PDAC malignancy." (PMID 24594697, 2014). "They demonstrated that CXCR4 expressing breast cancer cells preferentially migrated towards protein extracts of the lung, which expresses CXCL12 abundantly." (PMID 24390633, 2014). "It controls chemotaxis toward its ligand, CXCL12, which is highly expressed in the lung, bone, liver, and lymph nodes, organs to which breast cancer cells preferentially metastasizes." (PMID 25165728, 2014). "The ligand for CXCR4, CXCL12 mRNA, exhibited peak levels of expression in organs that are preferential destinations of breast cancer metastasis." (PMID 25237365, 2014). "Previous studies have shown that CXCR4 and its chemokine ligand 12 (CXCL12) are two key factors in breast cancer metastasis." (PMID 24475985, 2014). "This receptor is required for migration of breast cancer cells from the primary site to lung, bones, and lymph nodes, which represent organs that secrete high levels of chemokine CXCL12." (PMID 24591761, 2014). "We used combined treatment of TAM and TRAN to inhibit CXCR4 and CXCL12 protein and mRNA expression levels and determined the effects of these drugs on breast cancer metastasis." (PMID 25237365, 2014). "For example, it is reported that CXCL12 secreted by myofibroblasts has an important role in breast cancer tumorigenesis." (PMID 24978438, 2014). "The significance of the CXCL12/CXCR4 axis in breast cancer invasion and metastasis has been widely investigated." (PMID 24886617, 2014).
breast carcinoma (continued). "JWH-O15 inhibits hormone sensitive breast cancer metastasis by modulating CXCL12/CXCR4 signaling axis." (PMID 25115386, 2014). "We provide evidence that COUP-TFI increases the motility of MCF-7 ERα-positive breast cancer cells by acting on CXCL12/CXCR4 signaling as an endogenous target." (PMID 24906407, 2014). "Taken together, these results suggest that CXCR7 enhanced CXCL12-induced migration of breast cancer." (PMID 24886617, 2014). "CXCR4 (C-X-C chemokine receptor 4) is highly expressed in breast cancer cells, and its ligand (C-X-C motif chemokine 12, CXCL12) is expressed in high levels in tissues invaded by metastasis." (PMID 25147739, 2014). "The CXCL12/CXCR4 axis plays major roles in breast cancer cell proliferation, migration, and invasion; thus, we analyzed the CXCL12-mediated growth and motility of MCF-7 cells overexpressing COUP-TFI." (PMID 24906407, 2014). "In contrast, in breast cancer we found that while autocrine CXCL12 decreased hematogenous spread of tumor cells, it also increased proliferation of the primary mammary fat-pad-engrafted tumor." (PMID 24594697, 2014). "Conversely, T140 analogs are peptidic CXCR4 antagonists, originally developed as anti-HIV agents that inhibit CXCL12-induced migration of MDA-MB-231 breast cancer cells in vitro and mitigate pulmonary metastasis in vivo." (PMID 25165728, 2014). "The data also support the importance of the CXCR4/CXCL12 interaction in breast cancer metastasis, and further suggest that CXCR4 and CXCL12 are critical targets for tamoxifen and tranilast in combination or alone." (PMID 25237365, 2014). "For this reason, we decided to investigate the impact of COUP-TFI expression on the CXCL12 signaling axis in breast cancer cells." (PMID 24906407, 2014). "In contrast, the chemokine CXCL12, expressed at the surface of normal intestinal epithelium, is decreased in tumor tissues, such as colon or breast carcinomas." (PMID 24629239, 2014). "The positive CXCR4 protein expression was seen in 83/182 (45.6 %) cases of breast cancer and CXCL12 positive expression in 71/182 (39.0 %) breast cancer cases." (PMID 24810923, 2014). "Combination of TAM and TRAN induces more reduction in the secretion of CXCL12 by the breast cancer cells." (PMID 25237365, 2014). "Williams and colleagues reported that a CXCL12 analog with antagonist activity (CXCL12(P2G)) significantly inhibited metastasis in a syngeneic mouse model of breast carcinoma." (PMID 25165728, 2014). "Inhibition of the CXCL12/CXCR4 interaction by neutralizing antibody significantly impairs metastasis of breast cancer cells to regional lymph nodes and lung." (PMID 24915301, 2014). "CAFs have been recognized as important regulators of tumor initiation by secreting CXCL12 to activate CXCR4 on breast cancer cells and stimulate tumor growth." (PMID 25110692, 2014). "In this regard, the role of the CXCL12/CXCR4 axis in breast cancer invasion and metastasis is widely studied." (PMID 24886617, 2014). "It was also noted that COUP-TFI disturbs the estrogenic regulation of CXCL12 and CXCR4 in MCF-7 cells, supporting the idea that COUP-TFI leads to a loss of E2 dependency in breast cancer cells." (PMID 24906407, 2014). "The results of immunohistochemistry demonstrated CXCR4 and CXCL12 co-expression in 27.4% (50/182) breast cancer samples and the co-expression of CXCR4 and CXCL12 correlated with lymph node metastasis and TNM stage (p < 0.01)." (PMID 24810923, 2014). "The results of IHC revealed the membrane and cytoplasmic staining of the CXCR4 protein and the nuclear and cytoplasm staining of the CXCL12 protein in breast cancer." (PMID 24810923, 2014). "Chemo-attraction by lung tissue extracts was abolished by CXCL12-neutralizing antibodies and by preincubation of breast cancer cells with CXCR4-blocking antibodies." (PMID 24390633, 2014). "CXCR4 is a receptor for CXCL12 chemokine, which is secreted by the common sites of breast cancer metastasis, including lymph nodes." (PMID 24709997, 2014).
breast carcinoma (continued). "Similar CXCR4 tumor-promoting effects were observed in breast carcinoma, suggesting CXCL12 as possible autocrine/paracrine growth factor." (PMID 25484899, 2014). "Then, we detected the mRNA and protein expression of CXCR4 and CXCL12 in breast cancer cell lines by Western blot and RT-PCR." (PMID 24810923, 2014). "In marked contrast to our data in human colorectal or breast cancers, population growth of CXCL12 expressing PDAC was significantly decreased compared to chemokine deficient cells." (PMID 24594697, 2014). "Among the microenvironment signals sustaining the invasive phenotype of cancer cells, stromal cell-derived factor-1α (SDF-1α, also named CXCL12), plays a major role in promoting cancer metastasis in several cancers, including breast cancer." (PMID 24887021, 2014). "The chemokine CXCL12 is involved in the growth of many cancers including acute lymphoblastic leukemia, chronic B cell leukemia, glioma, breast cancer, ovarian cancer, small cell lung cancer, non-Hodgkin's lymphoma and colon cancer." (PMID 24259307, 2013). "Its ligand CXCL12, meanwhile, is preferentially expressed in the most common sites of breast cancer metastasis, lung, brain, lymph nodes, liver, and bone marrow." (PMID 24259307, 2013). "Conversely, other researchers demonstrated that co-expression of both CXCR4 and CXCR7 resulted in decreased CXCL12-mediated intravasation of mammary carcinoma cells and fewer metastases of these tumors to the lungs." (PMID 23847541, 2013). "In this article, we report that increased expression of CXCL12 by breast cancer cells can lead to enhanced in vivo invasion and increased macrophage and microvessel density." (PMID 22314082, 2012). "An important factor of the breast cancer cell-stroma crosstalk in the bone marrow is CXCL12, a chemokine that interacts with CXCR4 and CXCR7." (PMID 22482060, 2012). "The chemokine receptor CXCR4 and its ligand CXCL12 have been shown to mediate the metastasis of many malignant tumors including breast carcinoma." (PMID 22242160, 2012). "In vivo, neutralizing the interactions of CXCL12/CXCR4 significantly impairs metastasis of breast cancer cells to regional lymph nodes and lung." (PMID 23905066, 2012). "CXCR4 expression in breast cancer cells has been shown to increase metastasis by homing of tumor cells to sites of increased CXCL12 expression, such as the lymph nodes." (PMID 22314082, 2012). "By contrast, CXCL12 is highly expressed in the most common destinations of breast cancer metastasis including the lymph nodes, lung, liver, and bone marrow." (PMID 22485156, 2012). "A recent study identified certain microRNAs (miRNAs) which cross GJICs between breast cancer cells and stroma and specifically reduce CXCL12 levels." (PMID 22482060, 2012). "In our current study, we observed a dose- and matrix-dependent CXCL12-induced migration of breast cancer cells." (PMID 22253872, 2012). "Study in metastatic breast cancer revealed that the breast cancer cells high expression of CXCR4 metastasized to the corresponding target organs with high expression of CXCL12, such as lymph nodes and bone marrow." (PMID 22537906, 2012). "Inhibition of the pathway of CXCR4/CXCL12 would decrease breast cancer cells migration as well as vascular permeability." (PMID 23443093, 2012). "In summary, we have found that secretion of CXCL12 by breast cancer cells can enhance invasion in vivo and recruitment of macrophages to the primary tumor." (PMID 22314082, 2012). "CXCL12 and its receptor CXCR4 are implicated in the metastasis of several cancers including breast cancer metastasis to lung and lymph node." (PMID 23024796, 2012). "The attraction effect between CXCL12 and CXCR4 causes breast cancer cells and non-small cell lung cancer cells to migrate into brain, where cancer cells proliferate and form metastatic tumors." (PMID 23443093, 2012).